APOB (apolipoprotein B)
Diseases named in the same sentence as APOB in open-access papers (continued):
Sharing a sentence is not in itself a finding about the gene and the disease.
Hepatic steatosis (108 papers, 2010 to 2026). Steatosis is a term used to denote lipid accumulation within hepatocytes. "In liver-specific HuR-deficient mice, increased hepatic steatosis was accompanied by reduced expression of both APOB-100 and APOE, as well as decreased serum lipid levels." (PMID 40809813, 2025). "Hepatic secretion of VLDL is impaired in patients with ApoB mutations, which often leads to fatty liver disease because of the excessive intrahepatic accumulation of fat." (PMID 38195587, 2024). "Our proband had a novel heterozygous APOB variant causing significant liver steatosis, malabsorption of fat-soluble vitamins, and osteopenia." (PMID 37384046, 2023). "In fact, it is known that subjects with FHBL caused by truncating variants in the APOB gene are at increased risk to develop fatty liver because of a defective synthesis and export of VLDL from the liver, which causes an accumulation of TG in the hepatocytes." (PMID 34564380, 2021). "Altogether, our results indicate that ApoB deficiency results in impaired liver development accompanied by hepatic steatosis and disrupted intestinal architecture." (PMID 34236046, 2021). "In heterozygous carriers of a truncating variant in APOB, fatty liver disease associated with low plasma levels of total cholesterol, was reported." (PMID 32093271, 2020). "The overexpression of apolipoprotein B (ApoB) is associated with lipid accumulation and fatty liver diseases." (PMID 32863858, 2020). "Patients with familial hypobetalipoproteinemia often develop fatty liver due to mutations in the APOB gene, which either abolishes or interferes with the translation of full-length APOB protein, thus impairing lipid export from the liver." (PMID 30081561, 2018). "Elevated serum ApoB is associated with fatty liver and has been investigated as a possible biomarker." (PMID 27182456, 2016). "In the family study, APOB variants segregated with hepatic steatosis and fibrosis (P < 0.05)." (PMID 41665936, 2026). "MTTP I128T is associated with a reduction in hepatic steatosis, plasma lipids, and apoB." (PMID 40507973, 2025). "Together, these findings place ApoB at the intersection between hepatic lipid trafficking and systemic triglyceride excess, linking polygenic dyslipidemia to metabolic dysfunction-associated fatty liver disease (MASLD) and cardiometabolic risk." (PMID 41300829, 2025). "Dysfunctional apolipoprotein B (ApoB 100) secreted from APOB genetic variants leading to a series of impairments of lipid export from hepatocytes within very low-density lipoproteins are responsible for the development of severe hepatic steatosis." (PMID 37726886, 2023). "Loss of ApoB is also associated with on‐target adverse effects such as liver steatosis, possibly because all ApoB‐containing lipoproteins are targeted and there may be no mechanism by which the liver clears excess fat." (PMID 35712827, 2022). "Defects in production and/or secretion of ApoB lipoproteins are highly linked to hepatic steatosis." (PMID 34236046, 2021). "In addition, FHBL, which is associated with apolipoproteins and caused by mutations in APOB genes, results in increased risk of fatty liver, liver cirrhosis, and HCC18,40–44." (PMID 30429453, 2018). "Though it seems that increased ApoB levels would result in net lipid clearance from the liver, it is believed that the elevated ApoB associated with fatty liver arises secondary to increased hepatic TG, as VLDL synthesis is stimulated by TG, but is inadequate in clearing the elevated hepatic lipids." (PMID 27182456, 2016). "The hepatic secretion of VLDL is restrained by the inhibition of microsomal triglyceride transfer protein (MTP; gene name, MTTP), leading to an increase in hepatic steatosis and a reduction in serum lipids and apoB." (PMID 40507973, 2025). "Enhanced VLDL secretion is generally protective against hepatic steatosis, as evidenced by the increased prevalence of MASLD in individuals with loss-of-function mutations in MTTP or APOB." (PMID 40809813, 2025).
Hepatic steatosis (continued). "The critical role of ApoB-containing lipoproteins in mediating the export of intrahepatic lipids is underscored by the strong association between genetic variations in APOB or MTTP and the development of fatty liver disease." (PMID 40180213, 2025). "The hepatic methylation of male offspring showed an increase in the promoter region of the ApoB gene, reducing the ApoB level in serum and liver, thus contributing to hepatic steatosis." (PMID 38732634, 2024). "Historically, the apoB antisense mipomersen induced marked hepatic steatosis, but this was clearly an on-target effect of apoB inhibition." (PMID 37820081, 2023). "Hepatic steatosis and increased secretion of apolipoprotein B (apoB), especially very low-density lipoprotein (VLDL), cause both insulin resistance and ER stress." (PMID 37762367, 2023). "We have identified a novel pathogenic variant in the APOB gene causing FHBL in pediatric patients with hypocholesterolemia and fatty liver disease." (PMID 37384046, 2023). "Results showed that MBOAT7−/− and TM6SF2−/− models inhibited the release of both Apolipoprotein B and TAG-rich lipoproteins and reduced the risk and severity of fatty liver diseases." (PMID 36835291, 2023). "Specific deletion of MTTP in the liver causes hepatic steatosis and complete inhibition of VLDL and apoB secretion." (PMID 35740949, 2022). "Hepatic steatosis has been associated with genetic defects in both MTP and apolipoprotein B-100 (APOB), the hepatic VLDL lipoprotein." (PMID 33608323, 2021). "Her father (I.1) aged 61 years also presented low levels of lipid parameters (LDL-C levels of 0.64 mmol/L and ApoB levels of 0.17 g/L) and was also diagnosed with fatty liver detected by ultrasonography." (PMID 34564380, 2021). "It has been shown that the overproduction of the human APOB-100 protein in the liver leads to endoplasmic reticulum (ER) stress and insulin resistance and induces hepatic steatosis." (PMID 33919597, 2021). "Hepatic steatosis in HH is therefore rather related to iron-overload and subsequent oxidative stress with impaired apolipoprotein B100 (ApoB100) and VLDL secretion." (PMID 32680469, 2020). "Overall, treatment of PEG-BR in obese mice improved the hepatic steatosis potentially by utilizing fat for β-oxidation, increasing fatty acid uptake, reducing plasma ApoB-VLDL and triglycerides." (PMID 33390979, 2020). "When the TAG incorporation into VLDL is blocked by microsomal TAG transport protein (MTTP) and apolipoprotein B (APOB) mutations in patients, TAG accumulates in the liver and consequently causes hepatic steatosis and NASH development." (PMID 33372630, 2020). "As such, hepatic steatosis, secondary to compromised triglyceride export, is common in patients with genetic defects in the apoB or MTTP gene (hypobetalipoproteinemia and abetaproteinemia, respectively)." (PMID 29936596, 2018). "The patients of an ApoB-defective genetic form of familial hypobetalipoproteinemia frequently exerted fatty liver." (PMID 30060615, 2018). "Reduced hepatic steatosis along with increased hepatic insulin sensitivity and fatty acid oxidation can promote apolipoprotein B degradation, thereby contributing to lowering the secretion of LDL and LDL particle and circulating cholesterol level." (PMID 30327679, 2018). "Studies have shown that mutant apolipoprotein B (ApoB, the structural protein of VLDL) or MTP (responsible for recruitment of TGs) can cause hepatic steatosis by disrupting VLDL assembly." (PMID 30405443, 2018). "While the synthesis of apolipoprotein B and phospholipids is relatively reduced, finally lead to the deposition of triglycerides in liver and the onset of fatty liver." (PMID 30323178, 2018). "In both cases, defects in hepatic Apo B secretion result in very low levels of ApoB lipoproteins which are often accompanied by hepatic steatosis in addition to intestinal lipid and fat soluble vitamin malabsorption." (PMID 28300165, 2017).
Hepatic steatosis (continued). "This is consistent with a positive correlation between liver steatosis, hyperinsulinemia, and high plasma ApoB levels in humans and rodents." (PMID 26284027, 2015). "In fatty liver diseases there is accumulation of apolipoprotein-B with increased amounts of bisecting GlcNAc and the increased accumulation of apolipoprotein A-1." (PMID 24959592, 2014). "Research based on a lipid-induced ER stress model has shown that ER stress can inhibit apolipoprotein B 100 (apoB100) secretion in liver, which is the major factor promoting hepatic steatosis." (PMID 23762873, 2013). "Pathogenic variants were detected in the ABCB4 gene in a patient with idiopathic cholestasis, in the APOB and CP genes in a patient with hepatic steatosis, in the ABCB4 gene in a patient with elevated liver enzymes, and in the MTTP and AGL genes in a patient with cryptogenic cirrhosis." (PMID 40870862, 2025). "Carriers of APOA5, GPIHBP1, or LMF1 variants exhibited intermediate TG levels (1800–2500 mg/dL) and substantial pancreatitis risk, whereas APOB and APOC3 variant carriers had milder TG elevations (500–1500 mg/dL) but were more frequently associated with hepatic steatosis and metabolic comorbidities." (PMID 41300829, 2025). "Correspondingly, the APOB gene, which encodes the primary apolipoprotein for VLDL synthesis, was also dramatically decreased along with hepatic steatosis (13.4 times higher in the eCtrl group than eHS-II group, Padj < 0.05, β = 4, 483.77, post hoc Wilcoxon rank-sum test)." (PMID 38837944, 2024). "In this study, the induction of hepatic steatosis was effectively elicited by the high-fat diet, and the mRNA alterations of Mttp and ApoB were likewise elevated by the reference, indicating that the material may mitigate the symptoms." (PMID 39683561, 2024). "The potential t response heterogeneity to human ApoB and CETP transgenes in LGMD2B might be of interest ase ApoB dyslipoproteinemia is also prevalent in hepatic steatosis, fibrosis, and fat infiltration." (PMID 39138561, 2024). "Type 1 familial hypobetalipoproteinemia (FHBL1), characterized by low levels of apolipoprotein B (ApoB)-containing lipoproteins, elevation of transaminases, and hepatic steatosis, is a rare disease the prevalence of which is 1 in 3,000 among general population." (PMID 36003908, 2022). "Both mother and daughter should be evaluated for fatty liver disease due to lack of apoB protein produced from one allele." (PMID 37138899, 2022). "Dysfunction of the quality control mechanisms for ApoB may induce hepatic lipotoxicity, which is relevant to fatty liver disease, hepatic insulin resistance, and inflammation." (PMID 34492079, 2021). "Thus, the decrease in MTTP and ApoB expression found in our study suggests the severe progression of fatty liver disease." (PMID 33187321, 2020). "A recent study showed that mice fed a HF diet for 16 weeks exhibited reduced hepatic TAG production with an accompanying significant increase in hepatic steatosis, and reduced ApoB expression, suggesting that the decreased hepatic TAG production is due to a reduction in export." (PMID 28036028, 2016). "ER stress has been shown to increase VLDLR expression and inhibit ApoB secretion, which might be a primary mechanism of tunicamycin-induced hepatic steatosis under conditions of suppressed lipogenesis." (PMID 26540043, 2015). "Furthermore, increased plasma TAG was accompanied by reduced apoB protein expression in the liver, possibly inducing hepatic steatosis, leading the organism to chronic disease." (PMID 20920329, 2010). "Therefore, HCV infection-induced degradation of ApoB may contribute to hepatic steatosis and decreased lipoprotein secretion, but the mechanism of HCV infection-induced ApoB degradation has not been completely elucidated." (PMID 34492079, 2021).
Hepatic steatosis (continued). "Truncations in the ApoB cause a defective synthesis and export of VLDL from the liver, which causes an accumulation of triglycerides (TG) in the hepatocytes, and thus exposes those patients to an increased risk of developing fatty liver disease (up to a 60% prevalence)." (PMID 34564380, 2021). "Like our proband, their case also showed symptoms of steatorrhea, fatty liver, and low concentrations of TC, LDL-C, and apoB." (PMID 37384046, 2023). "Genetic defects in apoB (hypobetalipoproteinemia) and MTTP (abetalipoproteinemia) reduce VLDL secretion and hepatic steatosis." (PMID 35740949, 2022). "Under obese conditions, hepatic MDM2 overexpression leads to proteasomal degradation of ApoB, thereby lowering TG‐VLDL output, resulting in hepatic steatosis, oxidative stress, and inflammation." (PMID 35524581, 2022). "Deleting FGF21 from LSD1-LKO liver partially reversed the improved hepatic steatosis, likely due to the FGF21-dependent alteration of lipid uptake (Cd36) and secretion (ApoB, ApoA4, and ApoA5)." (PMID 34314389, 2021). "Thus, ApoB degradation might contribute to HCV infection-induced fatty liver." (PMID 34492079, 2021). "In conclusion, MEAO attenuates ER stress and prevents hepatic steatosis pathogenesis via inhibition of expression of the hepatic lipogenic genes and VLDLR, and enhancement of ApoB secretion." (PMID 26540043, 2015). "In conclusion, MEAO efficiently attenuated ER stress and prevented the development of hepatic steatosis through inhibition of the expression of hepatic lipogenic genes and of VLDLR, and enhancement of ApoB secretion." (PMID 26540043, 2015). "Together, these results suggest that MEAO attenuated ER stress and ameliorated hepatic steatosis via the downregulation of VLDLR expression, and the improvement of ApoB secretion under conditions of suppressed lipogenesis." (PMID 26540043, 2015). "Compared to the placebo, resmetirom significantly reduced LDL and non-HDL cholesterol, apolipoprotein B (ApoB), hepatic steatosis, and liver stiffness." (PMID 40141037, 2025). "The clinical presentation of FHBL varies, with heterozygous APOB-FHBL individuals usually being asymptomatic or exhibiting mild liver steatosis, often requiring no treatment." (PMID 38393015, 2024). "Our study reveals a novel mechanism of ApoB degradation and lipid accumulation during HCV infection and might suggest new therapeutic strategies for hepatic steatosis." (PMID 34492079, 2021). "The absence of both apoB isoforms resulted in low levels of TGs and cholesterol in circulation, accompanied by massive lipid droplet accumulation in hepatocytes, and liver steatosis." (PMID 34236046, 2021). "Our study revealed a novel mechanism for ApoB degradation and lipid accumulation during HCV infection and might suggest new therapeutic targets for hepatic steatosis." (PMID 34492079, 2021). "In HFD-fed mice, apigenin lowered plasma levels of free fatty acid, total cholesterol, apolipoprotein B and hepatic dysfunction markers and ameliorated hepatic steatosis and hepatomegaly, without altering food intake and adiposity." (PMID 27213439, 2016). "In addition to a reduction in diet-induced hepatic steatosis and adiposity, Our results also show that in addition to its hepato-protective effect, the ME improved a pro-atherogenic serum profile by lowering circulating PCSK9 and ApoB." (PMID 37242292, 2023). "Our results confirm that male APOB-100 transgenic animals show more severe metabolic disturbances after 7 months of an HFD compared to females, with regard to, for example, fasting glucose, serum triglyceride (TG), tumor necrosis factor α (TNFα) levels, and hepatic steatosis." (PMID 33919597, 2021). "In this study, we identified new mechanisms of ApoB degradation and HCV-induced lipid accumulation, and our findings might facilitate the development of novel therapeutic strategies for HCV infection-induced fatty liver." (PMID 34492079, 2021).
Hepatic steatosis (continued). "It is seemingly possible that the inhibition of DNL pathway may be resulted in the alleviation of liver steatosis by 20–30% because the mRNA expression level of ApoB was not differed by the isorhamnetin treatment." (PMID 31700054, 2019). "These conditions lead to hepatic steatosis, over-secretion of larger triglyceride (TG)-rich very low density lipoprotein 1(VLDL1) particles into the plasma, over-secretion of hepatic apolipoprotein B (ApoB), impaired clearance of chylomicrons and decreased receptor mediated endocytosis in the liver." (PMID 28376848, 2017). "HCV-G3 patients had significantly decreased serum apoB, non-HDL cholesterol concentrations, and more hepatic steatosis than those with HCV-G1." (PMID 35365728, 2022). "The findings have demonstrated that individuals chronically infected with HCV-G3 have significantly decreased serum apoB, and non-HDL cholesterol concentrations, in conjunction with more hepatic steatosis than those with HCV-G1." (PMID 35365728, 2022).